RNU4-92P (RNA, U4 small nuclear 92, pseudogene)
Gene: Small nuclear RNA gene on chromosome 14 (88,820,297 to 88,820,432, forward strand). Ensembl gene ENSG00000200653.
Homologues: Orthologues: chimpanzee U4 (99% identical), macaque U4 (86% identical), guinea pig U4 (51% identical), guinea pig U4 (43% identical). Paralogues in human: RNU4-68P (88% identical), RNU4-7P (88% identical), RNU4-13P (87% identical), RNU4-67P (85% identical), RNU4-58P (85% identical), RNU4-31P (82% identical), RNU4-42P (82% identical), RNU4-45P (82% identical), RNU4-76P (82% identical), RNU4-80P (82% identical), RNU4-8P (82% identical), RNU4-23P (81% identical), and 81 more.